ZNF695 (zinc finger protein 695)
Description:
May be involved in transcriptional regulation.
Synonyms: SBZF3
Tractability: PROTAC: ubiquitination databases record sites on it.
Gene: Protein-coding gene on chromosome 1 (246,945,547 to 247,008,093, reverse strand). Ensembl gene ENSG00000197472.
Subcellular location: Nucleus
Subcellular location (Human Protein Atlas): Nuclear speckles
Gene Ontology:
Molecular function: protein binding; DNA-binding transcription factor activity, RNA polymerase II-specific; RNA polymerase II cis-regulatory region sequence-specific DNA binding
Biological process: regulation of DNA-templated transcription; negative regulation of transcription by RNA polymerase II
Cellular component: nucleus
Genetic constraint (gnomAD): Loss-of-function variants: 10 observed, 8.91 expected, observed/expected ratio (o/e) 1.12, 90% interval 0.69 to 1.78. That is too few expected variants to judge how well the gene tolerates losing a copy. Missense variants: 554 observed, 610.06 expected, observed/expected ratio (o/e) 0.91, 90% interval 0.85 to 0.97. Synonymous variants: 189 observed, 208.27 expected, observed/expected ratio (o/e) 0.91, 90% interval 0.81 to 1.02.
Homologues: Orthologues: chimpanzee ZNF695 (98% identical), mouse Zfp738 (50% identical), mouse Zfp457 (46% identical), mouse Zfp595 (46% identical), rat AABR07009105.1 (43% identical), mouse Zfp953 (28% identical). Paralogues in human: ZNF681 (59% identical), ZNF682 (59% identical), ZNF724 (59% identical), ZNF708 (57% identical), ZNF726 (57% identical), ZNF85 (57% identical), ZNF429 (57% identical), ZNF254 (56% identical), ZNF728 (56% identical), ZNF727 (55% identical), ZNF595 (55% identical), ZNF43 (54% identical), and 164 more.
Diseases named in the same sentence as ZNF695 in open-access papers:
ZNF695 is named in the same sentence as 16 diseases in open-access papers, as found by Europe PMC text mining. Sharing a sentence is not in itself a finding about the gene and the disease. The quoted sentences say what the papers report.
ovarian carcinoma (5 papers, 2013 to 2022). A malignant neoplasm originating from the surface ovarian epithelium. "Previously, we identified the coexpression of three mRNA transcript variants of ZNF695 expressed in ovarian cancer, showing alternative 5’ splice sites in exon one and exon two." (PMID 31527520, 2019). "After that, we corroborated the amplification of three previously reported ZNF695 transcript variants in the cancer cell lines and malignant ovarian tumors." (PMID 31527520, 2019). "Here we describe some of the characteristics of ZNF695 mRNA splicing variants associated to ovarian cancer." (PMID 24007497, 2013). "The identity of ZNF695 AS variants was confirmed by cloning and sequencing of the amplicons obtained from ovarian cancer tissue and cell lines." (PMID 24007497, 2013). "Among the spectrum of several ovarian cancer-associated alternatively spliced genes, one mRNA, coding for ZNF695, a zinc finger protein, had the most significantly overexpression in OC with two prominent splice variants that were not present in normal ovarian tissue." (PMID 24007497, 2013). "Among several significantly overexpressed AS genes in malignant ovarian tumors and ovarian cancer cell lines, the most significant one was that of the zinc finger protein ZNF695, with two previously unknown mRNA splice variants identified in ovarian tumors and cell lines." (PMID 24007497, 2013). "Alternative ZNF695 mRNA splicing could be a marker of ovarian cancer with possible implications on its pathogenesis." (PMID 24007497, 2013).
breast carcinoma (3 papers, 2019 to 2022). "To identify full-length new transcript variants of ZNF695, we employed cancer cell lines with different tissue origins (cervical cancer, breast cancer and leukemia)." (PMID 31527520, 2019). "Its involvement in the stem cell phenotype was particularly evident in breast cancers, in which ZNF695 expression was the most abundant in basal‐like tumors, known for their high content of stem cells." (PMID 30444046, 2019). "Moreover, ZNF695 expression was higher in more aggressive basal‐like and HER2‐enriched breast cancers associated with early relapse and poor clinical outcome." (PMID 30444046, 2019). "In the breast cancer tissue panel (normal = 5, tumor = 43), we found that four KRAB‐ZNFs (ZNF205, ZNF273, ZNF485, ZNF695) were significantly upregulated in tumor tissue." (PMID 30444046, 2019). "(2015), who also revealed high levels of ZNF695 in basal‐like and HER2‐enriched tumors in three large breast cancer cohorts." (PMID 30444046, 2019). "For breast cancer, the number of KRAB‐ZNF‐positive samples was slightly different: (ZNF205 – 6/11, ZNF320 – 10/10, ZNF485 – 11/11, ZNF643 – 11/11, ZNF695 – 12/12, ZNF 707 – 10/10, and ZNF789 – 2/12)." (PMID 30444046, 2019). "Finally, these factors (ZNF273, ZNF485, ZNF695, ZNF643, and ZNF789), together with ZNF714, had significantly increased mRNA levels in the DNA methylation cluster 5 identified for breast cancer, which also coincides with the basal‐like subtype and the lowest overall DNA methylation level." (PMID 30444046, 2019). "The ZNF695 protein has been evaluated in breast cancer; interestingly, ZNF695 expression could classify the nonluminal A and luminal B subtypes." (PMID 31527520, 2019). "ZNF695 was also shown to upregulate cell cycle progression genes (e.g., CDK1, PLK1) cooperatively with other master regulators in nonluminal breast cancers." (PMID 30444046, 2019).
lung carcinoma (2 papers, 2019 to 2025). "Also, in lung cancer, ZNF695 might be indirectly associated with proliferation." (PMID 30444046, 2019). "In lung cancer tissue samples, KRAB‐ZNF staining was positive for at least four analyzed tumor samples (ZNF205 – 4/12, ZNF320 – 10/10, ZNF485 – 11/11, ZNF643 – 10/11, ZNF695 – 8/9, ZNF 707 – 10/11) and at least one sample from each set presented nuclear localization of a given factor." (PMID 30444046, 2019).
prostate carcinoma (2 papers, 2021 to 2022). A carcinoma that arises from epithelial cells of the prostate gland. "ZNF695 encodes the zinc finger family of proteins, whose function is not known, particularly in prostate cancer." (PMID 33995639, 2021).
acute lymphoblastic leukemia (1 paper, 2022). Leukemia with an acute onset, characterized by the presence of lymphoblasts in the bone marrow and the peripheral blood. "After 70 months of follow-up, ALPK1, ACTN4, CALR, and ZNF695 were identified as potential prognostic risk factors for adult acute lymphocytic leukemia in the overall survival analysis." (PMID 36139553, 2022). "ALPK1, ACTN4, CALR, ZNF695, and FBXL5 were identified as novel prognostic genes in relapsed acute lymphoblastic leukemia." (PMID 36139553, 2022).
B-cell acute lymphoblastic leukemia (1 paper, 2019). A neoplasm of lymphoblasts committed to the B-cell lineage, typically composed of small to medium-sized blast cells. "Additionally, we analyzed the expression of these six transcript variants in bone marrow from B-cell acute lymphoblastic leukemia patients and observed that ZNF695 transcript variants one and three were the predominant variants expressed in leukemia." (PMID 31527520, 2019).
breast tumors (1 paper, 2019). "Thus, it is tempting to speculate that ZNF695 may contribute to cancer stem cell identity, at least in basal‐like breast tumors." (PMID 30444046, 2019).
leukemia (1 paper, 2019). A malignant (clonal) hematologic disorder, involving hematopoietic stem cells and characterized by the presence of primitive or atypical myeloid or lymphoid cells in the bone marrow and the blood. "To date, no previous studies have identified and quantified the expression of novel ZNF695 transcript variants in childhood leukemia." (PMID 31527520, 2019). "Moreover, we found nine patterns of AS in association with the ZNF695 transcript variants expressed in leukemia patients." (PMID 31527520, 2019). "We discovered four novel ZNF695 alternative transcripts that are co-expressed in cell lines and leukemia patients." (PMID 31527520, 2019).
cancer (6 papers, 2019 to 2025). A tumor composed of atypical neoplastic, often pleomorphic cells that invade other tissues. "We designed specific primers to amplify previously reported alternative transcript variants of ZNF695 and showed that six ZNF695 transcript variants are co-expressed in cancer cell lines." (PMID 31527520, 2019). "For example, ZNF695 silencing causes a profound attrition in S, its expression is rhythmic, its binding sites overlap human-specific indels at promoters, and its expression is strikingly associated to proliferation across cancer types." (PMID 40555235, 2025). "Additionally, we observed the co-expression of six ZNF695 transcript variants in these cancer cell lines." (PMID 31527520, 2019). "The ZNF695 gene is transcribed as six alternative transcript variants in human cancer cell lines." (PMID 31527520, 2019). "The literature shows that some KZNFs are up-regulated in cancer, including ZNF695, ZNF320, ZNF200, ZNF354A, ZNF707, ZNF138 and so on." (PMID 37370088, 2023). "Surprisingly, we observed expression in both PCR assays, showing that ZNF695_TV1 and ZNF695_TV2 or ZNF695_TV3 are co-expressed in cancer cell lines." (PMID 31527520, 2019). "Here, we identified six AS transcripts of ZNF695 mRNA in cancer cell lines, including a B-ALL cell line." (PMID 31527520, 2019). "Lastly, ZNF519 ranked fourth behind ZNF695, ZNF724P, and ZNF93 among KZFPs whose expression correlated positively with proliferation across 33 TCGA cancer types, pointing toward a general association between proliferation, i.e., repeated cell cycling, and elevated ZNF519 expression." (PMID 40555235, 2025). "Out of all analyzed cancer‐associated KRAB‐ZNFs, ZNF695 seems to be the most interesting factor." (PMID 30444046, 2019). "Interestingly, cancer‐related upregulation of ZNF695, ZNF714, and ZNF138 mirrors the differential expression observed between pluripotent stem cells and differentiated cells." (PMID 30444046, 2019). "The expression of the lncRNA ZNF695 transcript in cancer has not been reported." (PMID 31527520, 2019).
tumor (6 papers, 2019 to 2025). "As expected, ZNF695 expression was strongly correlated with the expression of tumor proliferating markers." (PMID 40161734, 2025). "In this study, we found ZNF695 was overexpressed in PCa, which correlated with worse disease outcomes such as tumor progression and metastasis." (PMID 33995639, 2021). "Using high-density microarrays, we previously employed ovarian normal and tumor tissues to identify AS of ZNF695." (PMID 31527520, 2019). "Similar patterns were found between the ZNF695 expression and tumor L1 insertions." (PMID 40161734, 2025). "Considering the increased expression of ZNF695 in ER-negative tumors, it is tempting to speculate that its role in the cell cycle upregulation may be related to the aggressiveness of these tumor subtypes." (PMID 37492743, 2023). "TIMER tool further revealed expression of the 5 signature genes (ZNF695, CENPA, TROAP, BIRC5 and KIF20A) was strongly and positively correlated with high tumor purity but negatively influenced the infiltration of CD8+ T cells and macrophages." (PMID 33995639, 2021). "We also observed a negative correlation between the expression of ZNF695 and methylation level of L1 promoter in chr22q12.1 in tumor tissues but not in normal." (PMID 40161734, 2025). "Only ZNF695 exhibited a positive correlation between expression and tumor size in the BRCA tissue panel, but not in the TCGA dataset." (PMID 30444046, 2019).
ZNF695 also shares sentences with these, for which no sentence is quoted: adenocarcinoma (1 paper); cervical cancer (1); esophageal squamous cell carcinoma (1); lung adenocarcinoma (1); ovarian tumors (1); pancreatic cancer (1).